ALB (albumin)
Diseases named in the same sentence as ALB in open-access papers (continued):
Sharing a sentence is not in itself a finding about the gene and the disease.
nephrotic syndrome (continued). "Although the published data do not indicate any definitive conclusions about the benefits of albumin use in patients with nephrotic syndrome (NS), the guidelines recommend this procedure only in cases of edema that is refractory to use of diuretics." (PMID 28443947, 2017). "All five patients had nephrotic syndrome and 4 of these patients had serum albumin less than 2.5 g/dL." (PMID 27525120, 2016). "Various clinical trials regarding the use of albumin and furosemide to treat edema in patients with nephrotic syndrome have been published both in adults and children in an attempt to clarify if such a combination is beneficial in these patients." (PMID 26457719, 2015). "Albumin has been used to improve edema in patients with nephrotic syndrome in addition to diuretics." (PMID 26457719, 2015). "Data were similar between classes IVG and IVS, but patients with class IVS tended be less severe nephritis profiles including blood pressure, renal function, serum albumin, hemoglobin, and frequency of nephrotic syndrome." (PMID 25874130, 2015). "Eight patients with nephrotic syndrome and grossly apparent clinical edema were given three treatments with albumin alone, furosemide alone, and a furosemide-albumin combination." (PMID 26457719, 2015). "It is thought that a large amount of albumin leaking from the glomerulus in nephrotic syndrome (NS) is reabsorbed at the proximal tubule and catabolized." (PMID 25859658, 2015). "In conclusion, the use of albumin and furosemide remains a controversial therapeutic option in the management of edema in patients with the nephrotic syndrome." (PMID 26457719, 2015). "This study, therefore, suggests that the combination of albumin and furosemide therapy is effective only in patients whose nephrotic syndrome is in remission." (PMID 26457719, 2015). "In order to achieve sufficient diuresis and natriuresis in nephrotic syndrome patients, some investigators used the combination of furosemide and albumin, and reported variable results." (PMID 26457719, 2015). "Some authors have mentioned also decreased levels of albumin, possibly as a result of nephrotic syndrome or reduced synthesis of albumin by the affected liver." (PMID 26137342, 2015). "But several factors, including the half-life of serum albumin, disorders such as thyroid disease and nephrotic syndrome, have been identified to exert effects on GA." (PMID 25851542, 2015). "The effect of albumin and furosemide combination was also studied in children with nephrotic syndrome." (PMID 26457719, 2015). "Mean age, serum total cholesterol level, and proteinuria were higher and mean serum albumin level was lower in the patients with nephrotic syndrome than in the other groups." (PMID 25098821, 2014). "Protein resorption droplets have been found within podocytes in kidney biopsy specimens from patients and animals with nephrotic syndrome and podocytes have been shown to endocytose albumin in cell culture." (PMID 23382978, 2013). "In our work we used 5 mg/ml albumin (a dose similar to the concentration of albumin found in the urine of patients with nephrotic syndrome)." (PMID 23382978, 2013). "We exposed podocytes to a concentration of albumin (5 and 10 mg/ml) similar to that found in the urine of patients with nephrotic syndrome and used dextran of a similar molecular weight to albumin as an oncotic control." (PMID 23382978, 2013). "The levels of serum total protein and albumin were significantly lower, while the concentration of cholesterol and triglyceride were higher in acute phase of nephrotic syndrome than normal subjects." (PMID 24693505, 2013). "Podocytes contain increased amounts of albumin in kidney biopsies obtained from patients with nephrotic syndrome as well as in animals with heavy proteinuria." (PMID 23382978, 2013). "The patients with nephrotic syndrome and normal renal function have increased protein synthesis rates but inadequate responses to normalized serum albumin levels." (PMID 23245677, 2012).
nephrotic syndrome (continued). "There are several reports that platelet aggregation in patients with nephrotic syndrome and in patients on continuous ambulatory peritoneal dialysis, were inversely proportional to the serum albumin concentration." (PMID 24049653, 2012). "Fibrinogen levels correlate inversely with serum albumin levels in patients with nephrotic syndrome and in continuous ambulatory peritoneal dialysis patients." (PMID 24049653, 2012). "Another study was performed in 8 nephrotic syndrome patients with serum albumin ranging from 1.1-2.2 g/dL and impaired renal function (serum creatinine 1.2-2.39 mg/dL)." (PMID 22931630, 2012). "It is considered that a lower serum albumin level in the HPLF group indicates that nephrotic syndrome progressed further in the HPLF group than in the LPHF group." (PMID 21822358, 2011). "Each diet advanced the progress of nephrotic syndrome, as evidenced by serum albumin and urinary protein levels compared with the values at baseline." (PMID 21822358, 2011). "Patients who received IS treatment had lower serum albumin concentration than patients who received conservative treatment, indicating more severe nephrotic syndrome, whereas estimated glomerular filtration rate and the protein/creatinine ratio were not statistically different." (PMID 41510006, 2026). "As both the CRP/albumin ratio and fluid overload were parameters of interest in the study, the number of exclusion criteria was higher, reducing the generalizability to children with conditions like congenital heart disease or nephrotic syndrome." (PMID 39764324, 2025). "He relapsed with nephrotic syndrome in May 2019 with uPCR 1400 mg/mmol, serum albumin 19 g/L and PLA2R-positive at 41 RU/mL." (PMID 39979558, 2025). "The fact that this was more frequent in patients with lower serum albumin suggests that SGLT2 inhibitors may be less effective in patients with nephrotic syndrome." (PMID 40429528, 2025). "Compared to healthy volunteers, both MCD and MN groups of patients present with a typical picture of nephrotic syndrome, with very high proteinuria, decreased albumin and total protein levels, and marked dyslipidemia, including elevated total cholesterol, increased LDL, and higher triglycerides." (PMID 41373530, 2025). "Patients who were positive for anti-vinculin autoantibodies (n = 80) predominantly exhibited severe nephrotic syndrome, characterized by significantly higher urinary protein/creatinine ratio, lower serum albumin levels, and increased serum cholesterol and CD19 levels." (PMID 40463498, 2025). "Given the absence of hematuria, preserved serum albumin, and normal renal function, we did not suspect intrinsic renal disease or nephrotic syndrome as causes of hyponatremia in this case." (PMID 41267699, 2025). "A2M stands associated with steroid resistance in nephrotic patients and plays a central role in nephrotic syndrome because its macromolecular size and structure prevents it from passing through the slit diaphragm, even if other macroproteins such as albumin are lost in the urine." (PMID 39125467, 2024). "Moreover, oedema, hyperlipidaemia, and albumin reduction are less likely, which can differentiate Dent disease from nephrotic syndrome and Fanconi syndrome." (PMID 38267993, 2024). "Patients are considered at very high risk of progressive disease if they present with two or more of the following: a serum creatinine over 1.5mg/dL and higher, progressive decline in GFR by 25% over 2 years from the baseline or nephrotic syndrome defined by less than 2.5g/dL of albumin." (PMID 39759600, 2024). "Laboratory examinations were performed on admission, and nephrotic syndrome was diagnosed [creatinine: 168 μmol/L, estimated glomerular filtration rate (eGFR): 33 mL/min/1.73 m2, albumin: 18.5 g/L, total cholesterol: 6.86 mmol/L, urine albumin/creatinine ratio: 812.7 mg/mmol]." (PMID 40729293, 2024).
nephrotic syndrome (continued). "Participants with a serum albumin <3.5 g/dL at SGLT2i initiation were less likely to achieve a ≥30% reduction in proteinuria during follow-up, indicating limited response in those with active nephrotic syndrome." (PMID 39228996, 2024). "Studies using radioactive albumin in patients with nephrotic syndrome showed normal or increased plasma volume, implying that hypovolemia is only a minor cause of salt retention; thus, other possible mechanisms may be involved in salt and water retention." (PMID 38540182, 2024). "Notably, nephrotic syndrome, serum albumin, and serum IgG demonstrated significant correlations with PNI, GNRI, and CONUT score, while hemoglobin exhibited a moderate correlation with PNI and GNRI." (PMID 39149554, 2024). "In addition, dynamic-deficient podocytes exhibit the accumulation of blocked endocytic pits, and the accumulation of blue-labeled albumin endocytic vesicles was observed in podocytes from a rat model of nephrotic syndrome induced by puromycin." (PMID 37957688, 2023). "The trends in serum albumin and creatinine levels in the three groups were similar, suggesting that indobufen did not affect the efficacy of immunosuppressants in the treatment of nephrotic syndrome compared with warfarin." (PMID 36636998, 2023). "Low levels of albumin <20 (34-42 g/L) with raised urine/albumin ratio confirmed nephrotic syndrome." (PMID 37377976, 2023). "However, this examination cannot be used for patients affected by albumin metabolism disorders such as those with nephrotic syndrome, hyperthyroidism, and those receiving glucocorticoid treatment." (PMID 37370930, 2023). "The majority of patients with CNTN1 antibodies presented with a neuro-renal syndrome characterised by a rapidly progressive, disabling, sensory-motor neuropathy accompanied by typical nephrotic syndrome, with oedema, low serum albumin, and elevated levels of urinary proteinuria." (PMID 36893151, 2023). "This may be especially important in the case of proteinuria when the concentration of albumin in the urine is increased up to 100-fold during nephrotic syndrome or glomerulonephritis." (PMID 36979933, 2023). "Furthermore, we evaluated the effects of ACR, PCR, 24-h UP, and serum albumin levels on predicting IgA nephropathy progression in patients with nephrotic syndrome." (PMID 35295594, 2022). "Machine learning clustering was performed on 205 cases from the Japan Nephrotic Syndrome Cohort Study, whose clinical parameters, serum creatinine, serum albumin, dipstick hematuria, and proteinuria were traceable after kidney biopsy at 5 measured points up to 2 years." (PMID 35962244, 2022). "In nephrotic syndrome, serum A2M levels start to rise when a trace amount of albumin is excreted." (PMID 35327501, 2022). "**Including nephrotic syndrome (albumin excretion ACR > 2,220 mg/g)." (PMID 36523689, 2022). "In 33 cases presenting as nephrotic syndrome [as defined as gross proteinuria > 300 mg/dl (dipstick 3+/4+) and serum albumin <25 g/l], the response to 4 weeks of treatment with prednisone 1–2 mg/kg could be evaluated." (PMID 35386255, 2022). "In a study evaluating factors associated with complete remission, low albumin levels at baseline were associated with non-achievement of a complete remission and progression to nephrotic syndrome." (PMID 35172682, 2022). "Additionally, albumin concentrations are affected by many factors such as nutritional status and nephrotic syndrome." (PMID 36401181, 2022). "A meta-analysis supported that the use of Chinese herbal medicine as a treatment could increase plasma albumin, reduce urine albumin excretion and improve lipid metabolic disorder in the treatment of nephrotic syndrome." (PMID 33989325, 2021). "Six months after HSCT, the patient developed nephrotic syndrome, suspected to have resulted from the deposition of circulating soluble immune complexes in the glomerulus, and received multiple albumin infusions, furosemide, prednisolone, lisinopril, and bortezomib." (PMID 33407676, 2021).
nephrotic syndrome (continued). "A higher prevalence of DKD in the non-high AG group may be associated with both frequent ARB use and a relatively low range of serum albumin due to the frequent development of nephrotic syndrome." (PMID 33633262, 2021). "As is known to all, ALB encodes the most abundant protein in human blood, and bioinformatics analysis revealed that ALB was downregulated in FSGS, which is consistent with the clinical characteristics of known nephrotic syndrome." (PMID 35059432, 2021). "Studies of dyslipidemia in nephrotic syndrome, in which urinary albumin excretion is strongly increased, may be relevant for understanding these findings." (PMID 34151951, 2021). "A month after the beginning of treatment, the patient stopped taking the medication of his own accord and, when re-evaluated, he presented with recurrence of the nephrotic syndrome (uACR 3,800 mg/g, decrease of serum albumin from 3.5 to 2.2 mg/d, and fluid overload)." (PMID 34646728, 2021). "In the final Cox proportional hazard model, having undernutrition, high triglyceride level at initiation, baseline low serum albumin level ≤1.5 g/dl, and residing in rural areas were found to be independent predictors of relapse in children with nephrotic syndrome at 95% confidence level." (PMID 33299427, 2020). "However, there is inherent difficulty in making the diagnosis of nephrotic syndrome in pregnancy as physiological adaptation to pregnancy includes increased proteinuria, a fall in serum albumin concentrations, and peripheral oedema." (PMID 31672135, 2019). "Furthermore, incubation with plasma from patients with post-transplant recurrence of nephrotic syndrome increased albumin permeability in rat glomeruli compared to remission plasma." (PMID 29433915, 2018). "In multivariate analyses, the following parameters were included: Gender, age, glomerular filtration rate, and all nephrotic syndrome features (24 h urinary protein excretion, serum albumin, serum total cholesterol, LDL-cholesterol, HDL-cholesterol, and triglycerides)." (PMID 30384404, 2018). "Furthermore, supplementation was added to 0.8 diets in 10 patients presenting signs of protein-energy wasting, such as low body weight, low albumin level, or nephrotic syndrome." (PMID 30586894, 2018). "The aim here was to analyze albumin use among patients with nephrotic syndrome." (PMID 28443947, 2017). "37.3% of the patients had nephrotic syndrome (proteinuria ≥3.5 g/day and serum albumin ≤3.0 g/dl)." (PMID 27355365, 2016). "Clinical studies assessing use of furosemide and albumin in patients with nephrotic syndrome." (PMID 26457719, 2015). "Failure to address this issue could account for the persistent controversy regarding the use of albumin and furosemide in the nephrotic syndrome." (PMID 26457719, 2015). "ALB levels are decreased in chronic liver disease and nephrotic syndrome." (PMID 23741331, 2013). "In conclusion, we have found that albumin exposure at levels comparable to what is found in the urine of patients with nephrotic syndrome increased cell death, upregulated pro-inflammatory cytokines and upregulated pro-apoptotic pathways in a cultured podocyte-like cell line." (PMID 23382978, 2013). "Albumin is the major and most predominant plasma antioxidant which decreases during active phase of nephrotic syndrome and may be related to nephrotic syndrome." (PMID 24693505, 2013). "In addition, we confirmed some of our in vitro findings using a mouse albumin overload model as an in vivo model of nephrotic syndrome." (PMID 23382978, 2013). "Meanwhile, selective albuminuria in minimal-change nephrotic syndrome may be explained by the receptor-mediated transcytosis of albumin by podocytes, and this could be a new target for the treatment of the nephrotic syndrome." (PMID 22685655, 2012).
nephrotic syndrome (continued). "The effect of increased intratubular albumin which is found in severe nephrotic syndrome patients and which might blunt the response of furosemide was not prominent in our study since all the patients in our studies had 24-hour urine protein less than 3.5 g/d." (PMID 22931630, 2012). "The randomized trial evidence showing the capacity of hyperoncotic albumin to reduce edema is supplemented by non-randomized clinical studies and animal models in the areas of high-risk neonates, brain injury and nephrotic syndrome." (PMID 18318896, 2008). "Hyperoncotic albumin was investigated in three randomized trials of nephrotic syndrome." (PMID 18318896, 2008). "Only one patient who finally developed nephrotic syndrome, had low total protein and albumin." (PMID 18764935, 2008). "In addition, the severity of nephrotic syndrome was greater in the obinutuzumab or ofatumumab group than in the rituximab group (serum albumin 25.2 vs. 30.0 g/l and urine protein-to-creatinine ratio 5.9 vs. 5.7 g/g), although this was not statistically significant." (PMID 40225374, 2025). "Similarly, in certain medical conditions like nephrotic syndrome, large amounts of albumin are excreted, which may increase levothyroxine requirements due to binding of T4 to the excreted albumin." (PMID 36694248, 2023). "A 2-year-4-month-old girl was referred to our hospital about 1 month after the diagnosis of nephrotic syndrome with relapse had been made: urine protein-creatinine ratio markedly increased (749.1 mg/mg); blood urea nitrogen 11 mg/dL; serum creatinine 0.3 mg/dL; and serum albumin 1.8 g/dL." (PMID 33203378, 2020). "Moreover, patients with nephrotic syndrome who excrete large quantities of albumin may also have increased thyroxine requirements as a result of the binding of levothyroxine to the excreted albumin." (PMID 28695483, 2017). "Here we show in a cultured human podocyte line that exposure to levels of albumin similar to what might be seen in the glomerular ultrafiltrate of patients with nephrotic syndrome increases cell death, up-regulates pro-apoptotic pathways and up-regulates inflammatory cytokines." (PMID 23382978, 2013). "Although glomerular albumin filtration could be performed by the diffusion of albumin back and forth across the GBM, how albumin molecules can diffuse out across the effaced podocyte foot processes entirely covering the basement membrane in minimal-change nephrotic syndrome remains unclear." (PMID 22685655, 2012). "A recent large retrospective study found an eight times higher absolute risk of venous TEs in patients with nephrotic syndrome and the ratio of proteinuria to serum albumin, not serum albumin alone, predicted venous TEs in their cohort of patients with nephrotic syndrome of varied causes." (PMID 22963194, 2012). "Clinical studies show improved renal function: decreased creatinine in AKI, reduced albumin-to-creatinine ratio in CKD, and decreased proteinuria in nephrotic syndrome." (PMID 41669498, 2026). "SFN effectively relieved nephrotic syndrome, which was characterized by reduced 24 hr-UPro, T-CHOL, TG, HDL and LDL in the PHN+SFN group and increased ALB levels compared with those in the PHN group after eight days." (PMID 39850113, 2025). "PMN patients were presented with nephrotic syndrome, with a median urinary protein of 7.6 g/d (IQR 5.1, 8.2) and a serum albumin of 19.7 g/L (IQR 18.2, 23.7 g/L)." (PMID 40904455, 2025). "We found that patients with less severe nephrotic syndrome responded better to RTX, specifically those with lower baseline proteinuria and serum creatinine, and higher serum albumin levels." (PMID 41278312, 2025). "In addition, there were no comorbidities that could cause a decrease in albumin, such as nephrotic syndrome, persistent inflammatory disease, trauma, or hemorrhage." (PMID 38791890, 2024).